GPX4 (glutathione peroxidase 4)
Diseases named in the same sentence as GPX4 in open-access papers (continued):
Sharing a sentence is not in itself a finding about the gene and the disease.
glioblastoma (continued). "RAS-selective lethal 3 (RSL3), a well-known inhibitor of glutathione peroxidase 4 (GPX4), could effectively induce oxidative cell death in glioblastoma cells through ferroptosis, and several signaling pathways are involved in this process." (PMID 34987700, 2021). "Moreover, we found that increased ATF4 and xCT expression correlates with GPX4 knockdown, while ATF4 and xCT are considered to play a protective role against ferroptosis in glioblastoma cells." (PMID 34987700, 2021). "In the present study, we first discovered the effect of DHA in the glioblastoma lines U87, A172 by ferroptosis through Western blot, we found that DHA induced ferroptosis by down-regulating glutathione peroxidase 4 (GPX4), and this result was verified in immunofluorescence staining." (PMID 32452511, 2020). "Some tumors, such as glioblastoma, do not react well to single-agent GPX4 inhibitors." (PMID 40969276, 2025). "In glioblastoma (GBM), SELENOP maintains GPx1 and GPx4 levels, contributing to ferroptosis sensitivity and offering a potential target for overcoming drug resistance." (PMID 39942544, 2025). "Following 48 h of So exposure to A-172 glioblastoma cells, there was no significant change in the expression of genes encoding selenoproteins, and the level of genes encoding selenium-containing proteins GPX1, GPX4, TR1, and TR3 significantly increased." (PMID 36768736, 2023). "GPX4 knockdown alone can trigger ferroptosis in human fibrosarcoma, but our results indicate that GPX4 depletion is not sufficient to induce ferroptosis in glioblastoma, unless the NF-κB pathway is activated simultaneously." (PMID 34987700, 2021). "It was suggested that ferroptosis was a pivotal part and GPX4 was the critical target in the cell death on glioblastoma by DHA treatment, which provided the possibility and basis for the subsequent use of DHA for alternative or adjuvant therapy for glioblastoma." (PMID 32452511, 2020). "Compared to lung cancer and glioblastoma (GBM), which often rely on SLC7A11 and GPX4 overexpression for ferroptosis evasion, HNC appears to exhibit distinct ferroptosis resistance patterns through Nrf2-mediated transcriptional upregulation of FSP1, HO-1, and lipid metabolic enzymes." (PMID 40867889, 2025). "Additionally, their studies indicated that glioblastoma ferroptosis could not be efficiently induced by only knocking down the GPX4 gene." (PMID 40969276, 2025). "In glioblastoma multiforme (GBM) cells, FOXP3, belonging to the forkhead box (FOX) family, was found to upregulate the transcription of GPX4, but it also attenuated the degradation of GPX4 mRNA through the linc00857/miR-1290 axis, thereby suppressing ferroptosis and promoting proliferation." (PMID 39125992, 2024). "We found that the NF-κB pathway was activated in RSL3-treated glioblastoma cells, and NF-κB pathway inhibition could prevent RSL3-induced ferroptosis; however, GPX4 silencing alone did not induce ferroptosis, but combining NF-κB pathway activation with GPX4 depletion induced ferroptosis." (PMID 34987700, 2021). "However, in the presence of GPX4 knockdown, AR failed to induce the resistance to ALZ003, suggesting that ALZ003 inhibits glioblastoma through suppressing AR-mediated GPX4 expression." (PMID 31896509, 2020).
ovarian carcinoma (60 papers, 2013 to 2026). A malignant neoplasm originating from the surface ovarian epithelium. "BRCA1 deficiency results in GPX4 accumulation, conferring ferroptosis resistance and facilitating ovarian cancer progression." (PMID 40342999, 2025). "In ovarian cancer tissue, FZD7 can activate the carcinogen P63, enhance the expression of GPX4, prevent tumor cell ferroptosis, and decrease the susceptibility of drug-resistant ovarian cancer cells to ferroptosis." (PMID 39192972, 2024). "Consistent with our in vitro results, the SKOV3-bearing mouse group with high-dose SS administration showed GPx4 deficiency and reduced tumor growth compared with the vehicle-treated ovarian cancer mouse groups." (PMID 36768241, 2023). "Tripterygium glycosides, by targeting the NRF2/GPX4 signal axis, disrupt the stability of the oxidation restoration reaction and induce ferroptosis in ovarian tumor cells, thereby enhancing the chemical susceptibility of ovarian cancer to cisplatin." (PMID 39192972, 2024). "Notably, we found that high-dose SS induced lipid peroxidation, ferroptosis, and GPx4 deficiency in ovarian cancer cells." (PMID 36768241, 2023). "Interestingly, inhibition of GPX4 caused these platinum-tolerant (Pt-T) ovarian cancer cells to become more sensitive to platinum and undergo ferroptosis." (PMID 36438923, 2022). "Schematic diagram illustrating the mechanism whereby silent SREBP1 mediates the Nrf2/XCT/GPX4 pathway to induce ferroptosis in ovarian cancer cells." (PMID 41708586, 2026). "Mechanistically, SREBP1 silencing promotes ubiquitination-mediated degradation of the Nrf2 protein, thereby suppressing the expression of XCT and GPX4, ultimately triggering ferroptosis in ovarian cancer cells." (PMID 41708586, 2026). "Therapeutic synergy emerges from combined GPX4 inhibitor and PARP inhibitor treatment, which cooperatively induce ferroptosis in BRCA1-deficient ovarian cancer cells and potently inhibit tumor growth." (PMID 40342999, 2025). "We propose several drug combinations as potential therapeutic candidates in ovarian cancer, as well as GPX4 inhibitors as single agents." (PMID 40568132, 2025). "Recent studies indicate that the suppression of LIF/LIFR autocrine loops in ovarian cancer induces cell death by triggering ferroptosis through the downregulation of GPX4 levels." (PMID 40075639, 2025). "In homologous recombination proficient ovarian cancer cells, GPX4 inhibition significantly elevates intracellular ROS levels, subsequently inducing oxidative stress-mediated DNA double-strand break." (PMID 40342999, 2025). "The study demonstrates that combining GPX4 inhibitor with PARP inhibitor elicits synergistic efficacy in homologous recombination proficient ovarian cancer cells, distinguishing this mechanism from the ferroptosis pathway." (PMID 40342999, 2025). "In a study involving 192 ovarian cancer patients, high levels of GPX4 were associated with resistance to platinum-based drugs, and siRNA-mediated knockdown of GPX4 reduced the resistance of ovarian cancer cells to these drugs." (PMID 39045454, 2024). "Another study found that patients with epithelial ovarian cancer (EOC) and a high co-expression level of SLC7A11 and GPX4 had a 60-fold higher risk of developing platinum resistance compared with patients with a low level of co-expression." (PMID 38203758, 2024). "Pachymaran can induce ferroptosis by lowering NRF2 mRNA to raise Fe2+ and lower levels of NRF2,HO-1 and GPX4 proteins in ovarian cancer cells." (PMID 39192972, 2024).
ovarian carcinoma (continued). "In this study, BODIPY 581/591 C11 staining showed that niraparib plus POA markedly induced lipid peroxidation in ovarian cancer cells and inhibited the expression of GPX4, which detoxified phospholipid peroxidation and protected the cells from ferroptosis." (PMID 38798714, 2024). "This intriguing outcome suggests a potential interconnection between NRF2 and GPX4, hinting at a shared pathway in mitigating ovarian cancer progression." (PMID 38396022, 2024). "Our in vivo experimental data presents compelling evidence supporting the inhibitory effects of NRF2 or GPX4 inhibition on the growth and dissemination of ovarian cancer within the peritoneal cavity of mice." (PMID 38396022, 2024). "Our work indicated a clinical significance by targeting NRF2 and GPX4 which simultaneously trigger cell ferroptosis and apoptosis and synergistically eliminate ovarian cancer cells." (PMID 38396022, 2024). "As a Fenton reagent, iron nitroprusside, (FeNP) has a therapeutic effect on ovarian cancer organs originating from high-grade serous ovarian carcinoma (HGSOC) by inhibiting GPX4’s involvement in ferroptosis." (PMID 39192972, 2024). "The effect of GPX4 inhibition on HR-proficient ovarian cancer was determined by CCK-8 assay and flow cytometry." (PMID 39192643, 2024). "We tested the combination of NRF2-targeted inhibitors with GPX4-targeted inhibitors in ovarian cancer through in vitro and in vivo experiment." (PMID 38396022, 2024). "In summary, our findings suggested that combining NRF2 inhibitors and GPX4 inhibitors leads to synergistic inhibition of the growth of ovarian cancer by induction of ferroptosis as well as apoptosis." (PMID 38396022, 2024). "The use of inhibitors of SCD1 and FADS2 can reduce GPX4 activity and enhance the sensitivity of ovarian cancer cells to cisplatin." (PMID 39045454, 2024). "Inhibition of GPX4 interferes with intracellular iron homeostasis and increases lipid peroxide levels, inducing ferroptosis and exerting anticancer effects in ovarian cancer (Li, Zhang & Chao, 2021)." (PMID 36632137, 2023). "Lastly, we monitored the expression of GPX1, GPX4, and SELENOP genes in patients with ovarian cancer using the publicly available Oncomine database to elucidate the clinical significance of GPx4 in ovarian cancer." (PMID 36768241, 2023). "Here, we showed that high-dose SS inhibited the expression of GPx4, a ferroptosis inhibitor, in ovarian cancer cells in vitro." (PMID 36768241, 2023). "Oncomine revealed that the mRNA levels of GPx1 and GPx4 were strongly elevated in ovarian cancer tissues compared to those in normal ovarian tissues, whereas SELENOP levels were decreased in ovarian cancer tissues." (PMID 36768241, 2023). "The aim was to assess the expression levels of SLC7A11 and GPX4 in relation to platinum resistance and prognosis in patients with epithelial ovarian cancer (EOC)." (PMID 36485069, 2022). "Conversely, the inhibition of SLC7A11 and GPX4 decreased platinum resistance in ovarian cancer cells." (PMID 36485069, 2022). "Quantitative PCR analysis showed that SLC7A11 and GPX4 transcription were both upregulated in platinum‐resistant cell sublines compared with the parental ovarian cancer cell lines." (PMID 36485069, 2022). "In a recent study, GPX4 knockout reduced iron levels and decreased interleukin-6 and tumor necrosis factor expression in ovarian cancer cells." (PMID 36090052, 2022). "For in vitro experiments, SLC7A11 and GPX4 expression were both upregulated in platinum‐resistant cells compared with their parental ovarian cancer cells, and siRNA‐induced SLC7A11 and GPX4 inhibition decreased platinum resistance." (PMID 36485069, 2022). "SLC7A11 and GPX4 expression were both upregulated in platinum‐resistant cell sublines compared with their parental ovarian cancer cell lines, as determined via western blotting." (PMID 36485069, 2022).
ovarian carcinoma (continued). "Altretamine has been approved for the clinical treatment of ovarian cancer because it inhibits the activity of GPX4 to induce ferroptosis in ovarian cancer cells." (PMID 35264971, 2022). "In ovarian cancers, OCCC cells exhibited significantly higher sensitivity to GPX4 inhibitors and lower sensitivity to paclitaxel than other ovarian carcinoma lines in average in CTRP." (PMID 30962421, 2019). "Similarly, EC359 has been shown to induce ferroptosis by downregulating GPX4 levels in ovarian cancer cells." (PMID 40075639, 2025). "Ovarian cancer exhibits resistance to the taxol treatment through GPX4-mediated ferroptosis." (PMID 41049453, 2025). "So both single-agent inhibition of GPX4 and combinations may be particularly promising for pre-clinical studies in ovarian cancer." (PMID 40568132, 2025). "GPX4 knockout in ovarian cancer cell OVCAR-3 reduced the cell viability and colony formation." (PMID 41049453, 2025). "Therefore, the overexpression of SLC7A11 in ovarian cancer cells enhances GPX4 activity by increasing GSH levels, which assists cells in resisting ferroptosis and promotes cancer cell proliferation, invasion, and chemoresistance." (PMID 39045454, 2024). "Similarly, increased expression of SCD1 and fatty acid desaturase 2 (FADS2) leads to enhanced GPX4 activity, resulting in resistance to cisplatin in the ovarian cancer cell line PEO4." (PMID 39045454, 2024). "Overall, these findings suggest that combining NRF2 inhibitors with GPX4 inhibitors results in a synergy suppression of ovarian cancer in vitro and in vivo, and maybe a promising therapeutic strategy for the treatment of ovarian cancer." (PMID 38396022, 2024). "Our findings demonstrated that NRF2 promotes ovarian cancer survival and growth and targeting NRF2 with GPX4 inhibitors could exert a synergistic effect on ovarian cancer cells." (PMID 38396022, 2024). "Interestingly, CEBPG knockdown in A2780 and Hey ovarian cancer cells significantly decreased GPX4 and SLC7A11 expression." (PMID 38203758, 2024). "Therefore, the combination therapy involving NRF2 inhibitors and GPX4 inhibitors holds great promise as a therapeutic approach for the treatment of ovarian cancer." (PMID 38396022, 2024). "The results of multiple gene correlation analyses indicated that there was a significant linear relationship (positive correlation) between the expression of ATF4 in ovarian cancer tissue and the expression levels of GPX4, GSS, KEAP1, NFE2L2, SLC7A11, ATG3, ATG4D, and ATG5." (PMID 37215446, 2023). "The inhibition of glutathione peroxidase 4 (GPX4) can disrupt intracellular iron homeostasis and suppress lipid peroxide reducibility to induce ferroptosis, thereby inhibiting the proliferation and tumor growth of ovarian cancer." (PMID 36814203, 2023). "Recent studies have shown that FZD7 could inhibit ferroptosis in ovarian cancer through β-catenin/TP63/GPX4 pathway." (PMID 37060074, 2023). "RSL3 induces ferroptosis by inhibiting the GPX4 activity in drug-resistant ovarian cancer cells." (PMID 37842240, 2023). "In addition, in ovarian cancer tissue samples, the expression levels of GPX4 and SQSTM1 were about 8-fold higher than those of the other genes." (PMID 37215446, 2023). "Additionally, GPX4 has also been shown to be upregulated in platinum-tolerant ovarian cancer cells, which sensitizes them to GPX4 inhibitors." (PMID 35719967, 2022). "Neuroblastoma cell lines were, after ovarian cancer cell lines, the second most dependent on GPX4." (PMID 35484422, 2022). "Specifically, the percentage of SLC7A11 high‐expression ovarian cancer tissues with a high GPX4 expression was 60.47% (26/43 cases), whereas it was only 12.08% (18/149 cases) in SLC7A11 low‐expression tissues; this difference was statistically significant (p < 0.001)." (PMID 36485069, 2022).
ovarian carcinoma (continued). "Thus, our results suggest that a high co‐expression level of SLC7A11‐GPX4 was a superior predictor for poor prognosis and platinum resistance in ovarian cancer compared with the corresponding individual parameters (SLC7A11 or GPX4 expression)." (PMID 36485069, 2022). "Moreover, Ding and Lind showed that DHA treatment induced a 50% reduction of glutathione peroxidase-4 (GPx-4) protein expression and cytotoxicity in human ovarian cancer cell lines." (PMID 23762838, 2013). "However, some PYAGs with CNV gain, such as GSDMD, TP63, PRKACA, PJVK and CASP4, showed downregulated mRNA expression in ovarian cancers, and some PYAGs with CNV loss, such as IL18, GPX4, GZMA, NLRP6 and CASP6, showed upregulated mRNA expression in ovarian cancers." (PMID 36707884, 2023). "However, the link between SLC7A11 and GPX4 expression in platinum‐resistant ovarian cancer and its association with patient prognosis has not yet been reported." (PMID 36485069, 2022). "CYLD did not influence the expression levels of RIP3 (necrosis marker), p62 and ATG5 (autophagy marker), as well as levels of GPX4 and SLC7A11 (ferroptosis marker) in ovarian cancer A2780 and OVCAR3 cell lines." (PMID 40012003, 2025). "Emerging evidence implied that ovarian cancer cell encompasses the high oxidative pressure in peritoneal metastasis and activate the NRF2/GPX4 pathway to overcome lipid peroxidation." (PMID 38396022, 2024). "Since our data demonstrated that oxidative stress was lower in PBMCs from the participants with ovarian cancer, antioxidants, SOD2 and GPX4, were investigated as indicators of the mechanism responsible for a reduction in oxidative stress." (PMID 38168673, 2024). "Epithelial ovarian cancer patients with high co-expression of SLC7A11 and GPX4 are predicted to have unfavorable survival and platinum resistance." (PMID 37765018, 2023). "The results of cDNA expression profile analysis indicated that six genes, including GPX4, GSS, KEAP1, SQSTM1, SLC7A11, ATG3, and ATG5, were highly expressed in tumor tissues from patients with ovarian cancer." (PMID 37215446, 2023). "Finally, we explored whether factors such as ATF4, GPX4, GSS, KEAP1, NFE2 like BZIP transcription factor 2 (NEF2L2), SLC7A11, SQSTM1, ATG3, ATG4D, and ATG5 have potential as non-invasive diagnostic markers for ovarian cancer." (PMID 37215446, 2023). "The results of the data analysis indicated that the contents of ATF4, GPX4, GSS, KEAP1, and ATG3 in the peripheral blood exosomes of patients with ovarian cancer were significantly higher than those of the healthy controls." (PMID 37215446, 2023). "In this study, we evaluated the predictive prognostic value of the ferroptosis‐related protein GPX4 and the ferroptosis‐inducing agent SLC7A11 in ovarian cancer." (PMID 36485069, 2022). "Firstly, to identify the connection among SNAI2, ferroptosis and ovarian cancer, the expression level of SNAI2, SLC7A11 and GPX4 in human normal ovarian cell line IOSE-80 and multiple ovarian cancer cells were detected." (PMID 35220872, 2022). "Carboxymethylated pachyman (CMP) inhibited HO-1 signaling, xCT, and GPX4, as well as upregulated Fe2+ expression by downregulating NRF2 expression, ultimately leading to the induction of ferroptosis in ovarian cancer cells." (PMID 36090052, 2022).